CR1 (complement C3b/C4b receptor 1 (Knops blood group))
Diseases named in the same sentence as CR1 in open-access papers (continued):
Sharing a sentence is not in itself a finding about the gene and the disease.
tumor (continued). "Multivariate Cox-regression analysis showed that only the depth of tumor invasion (HR = 1.465, 95% CI = 1.655–6.395, p = 0.018) and the expression of CR-1 (HR = 3.253, 95% CI = 1.066–1.2.011, p = 0.001) were independent prognostic indictors in ESCC patients." (PMID 28431580, 2017). "We demonstrated that the most ESCCs had positive CR-1 expression, which is closely related to the depth of tumor invasion, lymph node metastasis and poor prognosis in the ESCC patients." (PMID 28431580, 2017). "CR-1 also shows promise as a tumor-specific biomarker for the early detection of carcinomas as well as a target for chemotherapeutic development." (PMID 26472984, 2015). "Interestingly, we also define a new state of “Anatomical Separation” in a few human tumors studies that reveal CR1 expression in the endothelial cells of the tumor vascular bed and CR3 expression in the main tumor body." (PMID 39518018, 2024). "IHC staining results of pathological tissue reveal a diverse anatomical CR1/CR3 expression where some tumors express both proteins, others selectively express only CR3, and still others show that endothelial cells of the vascular tumor bed stain for CR1 while tumor cells express CR3." (PMID 39518018, 2024). "Their clone 35 antibody had a 1.1 pmol affinity, could detect CR1 in both human tumor cell lines and tumor tissue, and could suppress the in vitro growth of human colon cancer cell line GEO." (PMID 39518018, 2024). "It has been previously reported that CR1 functions as a tumor angiogenesis factor." (PMID 39518018, 2024). "In addition, a newly coined terminology was established, “Anatomical Separation”, to describe a solid tumor phenomenon where CR1 stained endothelial cells of the vascular tumor bed while CR3 stained the main tumor body." (PMID 39518018, 2024). "The overexpression of CR‐1 protein in tumours may promote cell proliferation, invasion, migration and tumour angiogenesis." (PMID 37528674, 2023). "Specific CR‐1 staining was mainly located in the cytoplasm of tumour cells." (PMID 37528674, 2023). "We found that the mRNA expression of C1QA, C1QB, C1QC, C5AR1, C3AR1, C1QR (CD93), CR1, CR2, CR3 (ITGAM), and CR4 (ITGAX) were positively associated with almost all kinds of tumor immune cells, including CD8+ T cells, CD4+ T cells, B cells, macrophages, monocytes and DCs." (PMID 34813686, 2022). "Previous studies have shown that CR‐1 expression is related to tumor prognosis." (PMID 35949510, 2022). "Furthermore, qRT-PCR analysis confirmed that relative CR-1 mRNA expression levels were significantly higher in HCC tissues compared to the adjacent non-tumor liver tissues." (PMID 34517344, 2021). "Moreover, CR-1 mRNA levels were up-regulated in HCC tissues from the TCGA datasets compared to the non-tumor liver tissues." (PMID 34517344, 2021). "CR‐1 plays an important role in tumorigenesis by promoting cell proliferation, survival, migration and invasion, inducing epithelial to mesenchymal transition, transformation, branching morphogenesis and tumour angiogenesis." (PMID 32697011, 2020). "The protein expression of CR‐1 in the tumours was detected by immunohistochemistry." (PMID 32697011, 2020). "Larger studies are clearly warranted and may help to elucidate important potential cut points to translate CR-1 into the clinical arena as a serum tumor marker." (PMID 31455359, 2019). "CR-1 expression was elevated in ccRCC tumor tissues and serum samples." (PMID 31455359, 2019). "CR-1 expression was correlated with aggressive tumor phenotype and poor survival." (PMID 31455359, 2019). "Moreover, CR-1 shRNA led to a significant reduction of the tumor weight as assessed at the completion of the experiment when compared to control group (P < 0.01)." (PMID 31455359, 2019). "Accumulating evidence has demonstrated that high expression of CR-1 might be a key alteration contributing to the invasion and metastasis of tumor cells." (PMID 31455359, 2019).
tumor (continued). "The results showed that CR-1 was primarily localized in the cytoplasm of tumor cells." (PMID 31455359, 2019). "Next, we studied the in vitro effect of CR-1 on tumor angiogenesis by HUVECs tube formation assay." (PMID 31455359, 2019). "This implies the potential role of CR-1 as a main modulator of tumor blood vessel formation." (PMID 31455359, 2019). "Moreover, high CR-1 serum levels were markedly correlated to high CR-1 expression in tumor tissues as evaluated by IHC (Pearson correlation coefficient = 0.735, P < 0.001)." (PMID 31455359, 2019). "In contrast, strong CR-1 staining was observed in ESCC tumor tissues and metastatic lymph node." (PMID 28431580, 2017). "In a separate set of samples, quantitative analysis of CR-1 mRNA in 11 fresh surgical tumor specimens and the adjacent normal tissues indicated that 10 out of 11 tumor specimens had high level of CR-1 expression (2 ~ 18 fold higher) as compared to their adjacent normal tissues." (PMID 28431580, 2017). "Nevertheless, we should consider the possibility that Nodal might function in conjunction with CR-1 at a specific time or in certain tumor subpopulations that may have cancer stem-like properties and that have the capacity to promote tumor development." (PMID 25596738, 2015). "However, experimental studies using tumor cells have demonstrated that CR-1 is closely regulated by transforming growth factor (TGF)-β superfamily members, and particularly by TGF-β1 and bone morphogenetic protein (BMP)-4, both expressed by endometrial cells." (PMID 25165718, 2014). "In addition, the results suggest that serum CR‐1 was a marker of tumor recurrence." (PMID 35949510, 2022). "However, high CR-1 expression was also observed in 39 adjacent non-tumor tissues in our study." (PMID 31455359, 2019). "The CR-1 serum levels were remarkably decreased compared to their preoperative serum by the 4th week after operation (P < 0.001), suggesting that CR-1 could reflect tumor burden." (PMID 31455359, 2019). "Evidence suggests that CR-1 might have a role in the invasiveness of tumour cells." (PMID 21863025, 2011). "Targeting the CSC/EMT antigen Cripto-1 (Cr-1) in the 4T1 model or the xCT protein, also known as SLC7A11, in the 4T1 or TUBO models with a plasmid-based vaccine inhibited tumor growth by about 30–40% and significantly reduced metastatic spread to the lungs." (PMID 40432134, 2025). "In 400+ cases of human tumor tissues examined by IHC, CR3 staining was always the most prevalent and most intense when compared to CR1." (PMID 39518018, 2024). "Using our selective MoAbs for WB, we demonstrated that CR1 and CR3 are expressed by human tumor cell lines." (PMID 39518018, 2024). "The Biogen company has dissected the entire human CR1 molecule with a series of mouse MoAbs, some of which targeted both the EGF-like domain and CFC domains and have proven to block human tumor cell growth in cell culture and in xenograft nude mouse models." (PMID 39518018, 2024). "Our IHC studies for CR1/CR3 expression in paraffin-embedded samples of human tumor tissue have demonstrated diverse staining patterns where some tumors only have CR3, while other cases show a dual expression of both CR1 and CR3 in the tumor." (PMID 39518018, 2024). "Using our discriminatory anti-CR1 versus anti-CR3 MoAbs, we evaluated several human tumor cell lines for the expression of said oncofetal proteins." (PMID 39518018, 2024). "Collectively, these data suggested that SF-CR-1 was the predominant CR-1 transcript in majority of the HCC cell lines, HCC and adjacent non-tumor liver tissues." (PMID 34517344, 2021). "However, the mechanism of the role of CR‐1 in the tumours metastasis remains unknown." (PMID 32697011, 2020). "We found substantial changes of both DNA methylation and mRNA expression of CR1, ESR1, PTPN13, and SOCS2 in HCCs compared with paired non-tumor tissues, which is consistent with the results obtained by analyzing the array data in our discovery sample." (PMID 25965583, 2015).
tumor (continued). "In C1-GBM, key tumor driver genes included BIRC3 (Baculoviral IAP Repeat Containing 3), MET (MET Proto-Oncogene, Receptor Tyrosine Kinase), COL1A1 (Collagen Type I Alpha 1 Chain), CR1 (Complement C3b/C4b Receptor 1), and IL7R (Interleukin 7 Receptor)." (PMID 41614933, 2026). "Our anti-CR1 NCI 5G1-1 MoAb identified a band at 50 kDa MW that varied in intensity for all human tumor cell lines tested, although being almost absent in hmVEC cells." (PMID 39518018, 2024). "Furthermore, when tumor cells stained for both proteins, the staining was always cytoplasmic, and CR3 had a more granular pattern, whereas CR1 staining was more diffuse." (PMID 39518018, 2024). "Dual immunofluorescence for CR-1 and vimentin, in most instances, showed the absence of vimentin in tumor cells while expression was found in the stromal contingent." (PMID 25596738, 2015). "CR-1 expression was especially high in a number of tumor specimens compared to non-malignant prostate specimens." (PMID 25596738, 2015). "In addition, previous studies have illustrated that CR-1 plays an oncogenic function during carcinogenesis by boosting cell proliferation, survival, migration and invasion, as well as inducing epithelial-to- mesenchymal transition (EMT) and tumor angiogenesis." (PMID 31455359, 2019). "We next randomly selected 8 genes aberrantly expressed in HCCs that had aberrant DNA methylation (CR1, ESR1, PTPN13, and SOCS2) or SCNA (C8A, CXCL14, ITGA6 and MARCO) to validate the array-based results in an independent sample set consisting 47 HCCs and paired non-tumor specimens." (PMID 25965583, 2015). "Hence it is not inconceivable that CR1 produced by endothelial cells could play a similar role in maintaining tumor vascular integrity." (PMID 39518018, 2024). "In addition, while CR-1 has multiple signaling mechanisms that may contribute to tumor progression, its known cell surface binding partners do not appear to fully explain its reported oncogenic functions." (PMID 31455359, 2019). "Given the small sample size of human tumor cell lines examined by WB and even though CR1 appears to be more prevalently expressed than CR3, no definitive conclusions should be drawn until a more diverse and larger tumor cell line number is examined." (PMID 39518018, 2024). "In this present work, we demonstrated that a mutant adenoviral E1A (mE1A) deletion of portion CR1 and CR2 (30-60aa and 120-127aa) can selectively inhibit tumor cell growth, but had no cytotoxic effect on normal cells, while the wild type E1A induced normal cells death dramatically." (PMID 27340782, 2016). "Immunohistochemistry showed that CR-1, E-cad, and N-cad expression mainly localized in the ESCC cell membrane and Vim expression mainly localized to the ESCC cytoplasm, while normal cells around the tumor margin were weakly positive or negative (, –4)." (PMID 26472984, 2015).
infection (45 papers, 2007 to 2026). The state of being infected such as from the introduction of a foreign agent such as serum, vaccine, antigenic substance or organism. "These in vitro findings triggered us to test CR-1 for virulence potential and inflammatory response associated with colistin resistance in a mouse infection model." (PMID 36188613, 2022). "Despite the importance that CR1 polymorphisms may have in the establishment of infection, only one association study on five missense mutations in this gene, has been conducted." (PMID 30092084, 2018). "Therefore, the C4d/CR1 ratio can serve as a useful marker to differentiate between fever caused by infection and that caused by flare-up in SLE patients." (PMID 26273660, 2015). "CR1 alleles associated with a low CR1-expression phenotype may exert a beneficial effect in populations exposed to P. vivax by reducing the efficiency of invasion, and thus decreasing the risk of infection and disease." (PMID 31221984, 2019). "E3-11.6K/ADP, the only CR1 gene with a known function encoded in the HAdV-C genome between E3-19K and RIDα, is expressed at late stages of infection and facilitates the efficient release of virus progeny at the end of the virus life-cycle through an unknown mechanism." (PMID 22882760, 2012). "Blocking antigen binding to complement receptor type 2 and 1 (CR2/CR1) prior to infection with FMDV significantly reduced the detection of viral proteins on FDCs and FMDV genomic RNA in spleen samples." (PMID 35512014, 2022). "WNV infection in mice deficient in complement receptor 1 (CR1) and CR2 developed increased CNS virus burdens, and were vulnerable to lethal infection at a low dose of WNV, and had significant deficits in IgM and IgG." (PMID 31623175, 2019). "Interaction between gp350/220 and complement receptor type 2 (CR2)/CD21 and/or (CR1)/CD35 on B-cells is required for infection." (PMID 25885535, 2015). "In our study, some febrile SLE patients had definitive evidence of infection and also elevated C4d/CR1 ratio, indicating the presence of flare-up with infection." (PMID 26273660, 2015). "In conclusion, the C4d/CR1 ratio is a simple and quickly determinable biomarker to differentiate between infection and flare-up in febrile patients with SLE." (PMID 26273660, 2015). "In contrast, high SLEDAI scores were obtained in patients with low C4d/CR1 ratios in patients with definitive infection." (PMID 26273660, 2015). "The upregulation of genes encoding B cell surface molecules—including CD19, MS4A1, CD22, FCER2, and CR1—may be involved in the proliferation and differentiation of memory B cells induced by the vaccine doses, following BA.5 infection." (PMID 39499071, 2024). "Like most of the other CR1 proteins E3/49K is a type I transmembrane protein starting to be expressed at early stages of infection, but continues to be expressed throughout the infection cycle." (PMID 39139562, 2024). "The complement receptor 1 (CR1) serves as a gate for bacterial entry in macrophages, but its importance in the spread of infection and emergence of symptoms is unknown." (PMID 30092084, 2018). "This study aimed to determine whether the ratio of the level of erythrocyte-bound C4d to that of complement receptor 1 (C4d/CR1) can serve as a useful biomarker in the differentiation between infection and flare-up in febrile SLE patients." (PMID 26273660, 2015). "In SLE patients with HA, the C4d/CR1 ratio may be higher than expected, which may lead to overestimation of disease activity; in these patients, the C4d/CR1 ratio is too high to differentiate between flares-up and infections." (PMID 26273660, 2015). "This supports the plausibility that CR1 might interact with Rv1589 during the infection of M. tuberculosis." (PMID 24708540, 2014).
infection (continued). "A cytometry adhesion inhibition assay was performed with sera from individuals suffering P. vivax malaria to determine whether the antibodies produced during natural infection could inhibit functional conserved regions (CR1 and CR2) interaction with reticulocytes." (PMID 28526096, 2017). "For instance, the CR1 and TMEM121 loci have been shown to be adapted to pathogen infection in South China41." (PMID 37479695, 2023). "Subsequent studies confirmed that CR1 (CD35) and DARC were responsible for HIV-1 binding to the erythrocytes and virus trans-infection of target cells." (PMID 31772057, 2019). "Our KEGG pathway enrichment analysis indicates that the up-regulated DEGs including C3, PLG, CFD, CR1, and C1QB are still enriched in complement and coagulation cascades, up to 24 h after infection." (PMID 31316336, 2019). "Among these receptors, CR1 and CR2 on monocytes are involved in phagocytosis via interactions with the C3 complement during infection." (PMID 31616424, 2019). "Similarly, infection-associated morbidity is not different between WT and CR1/2−/− mice." (PMID 29581196, 2018). "Our results indicate that the C4d/CR1 ratio can serve as a predictor of infection in febrile SLE patients, thereby enabling the differentiation between infection and flare-up in febrile SLE patients." (PMID 26273660, 2015). "Given the rapid (within 1 hr) increase of neutrophil CCR3 surface expression upon STm infection, we hypothesized that CCR3, akin to CR1, may be stored intracellularly in neutrophils, consistent with reports of intracellular CCR3 in eosinophils." (PMID 39193987, 2024). "Binding of HIV to CR1/DARC demonstrates that HIV might exploit CR1/DARC to its advantage as a unique niche that enables viral survival and trans-infection of HIV target cells." (PMID 31772057, 2019). "Our observations do not exclude DARC and CR1 as possible RBC binding sites since a partial reduction in HIV trans-infection occurred when the anti-CR1 antibody was applied." (PMID 31772057, 2019). "Similarly, despite previous reports for the role of CR1 in RBCs for enhanced HIV infectivity of target cells, in our hands, anti-CR1 antibody had moderate preventive effects on HIV trans-infection by RBCs." (PMID 31772057, 2019). "Febrile SLE patients without infection had a higher C4d/CR1 ratio than those with infection (3.34 ± 2.17 versus 0.80 ± 0.91, P < 0.001)." (PMID 26273660, 2015). "We noted a significant difference of the C4d/CR1 ratios between groups: febrile SLE patients without infection had significantly higher C4d/CR1 ratios than those with infection at initial admission (P < 0.001)." (PMID 26273660, 2015). "Further, the C4d/CR1 ratio was significantly different between febrile SLE patients with infection and febrile non-SLE patients and between the former and healthy controls (P < 0.001)." (PMID 26273660, 2015). "Administered before infection, neither anti-CR1 (CD35) nor anti-CR3 (CD11b) affected the stimulatory capacity of monocytes, as evaluated by expression of CD86, CD40 and HLA-DR (data not shown)." (PMID 25061945, 2014). "Mice with depleted complements, or lacking B cells, FcγR1, CR1, CR2, or Nox2 (a subunit of NADPH oxidase) are more susceptible to non-lethal dose infection with the HF strain of Ehrlichia (Ixodes ovatus Ehrlichia) that is closely related to E. chaffeensis." (PMID 24098122, 2013). "This is in line with our results where neutralising antibody responses up to day 7 post infection were similar in mice with or without a CR2/CR1 block, yet after this timepoint, there was a significant reduction in FMDV neutralising antibodies in mice treated with the anti-CR2/CR1 mAb." (PMID 35512014, 2022). "The C4d/CR1 ratio was the highest in febrile SLE patients without infection (P < 0.001)." (PMID 26273660, 2015). "The range of the C4d/CR1 ratio in the febrile SLE patients without infection was 0.68–8.80 and that in the febrile SLE patients with infection was 0.03–3.51." (PMID 26273660, 2015).